HIGD2B (HIG1 hypoxia inducible domain family member 2B)
Synonyms: HIGD2BP
Tractability: Antibody: UniProt predicts a signal peptide or a membrane-spanning region.
Gene: Protein-coding gene on chromosome 15 (72,675,798 to 72,686,182, reverse strand). Ensembl gene ENSG00000175202.
Subcellular location: Membrane
Subcellular location (Human Protein Atlas): Mitochondria; Cytosol
Gene Ontology:
Molecular function: protein binding
Biological process: mitochondrial respirasome assembly
Cellular component: mitochondrion; membrane
Homologues: Orthologues: chimpanzee HIGD2B (98% identical), mouse Higd2a (75% identical), dog HIGD2A (73% identical), guinea pig Higd2a (73% identical), rat Higd2a (72% identical), pig HIGD2A (71% identical), rat AABR07035091.1 (71% identical), zebrafish higd2a (53% identical), tropical clawed frog higd2a (47% identical). Paralogues in human: HIGD2A (78% identical), HIGD1B (29% identical), HIGD1A (28% identical), HIGD1C (26% identical).